ZC3H8 (zinc finger CCCH-type containing 8)
Description:
Acts as a transcriptional repressor of the GATA3 promoter. Sequence-specific DNA-binding factor that binds to the 5'-AGGTCTC-3' sequence within the negative cis-acting element intronic regulatory region (IRR) of the GATA3 gene (By similarity). Component of the little elongation complex (LEC), a complex required to regulate small nuclear RNA (snRNA) gene transcription by RNA polymerase II and III. Induces thymocyte apoptosis when overexpressed, which may indicate a role in regulation of thymocyte homeostasis.
Synonyms: ZC3HDC8; Fliz1
Tractability: PROTAC: UniProt records ubiquitination sites on it; ubiquitination databases record sites on it.
Gene: Protein-coding gene on chromosome 2 (112,211,529 to 112,255,151, reverse strand). Ensembl gene ENSG00000144161.
Subcellular location: Nucleus
Subcellular location (Human Protein Atlas): Nucleoplasm; Nuclear bodies
Pathways (Reactome):
Gene expression (Transcription): RNA polymerase II transcribes snRNA genes
Gene Ontology:
Molecular function: protein binding; RNA binding; DNA-binding transcription repressor activity, RNA polymerase II-specific; metal ion binding; RNA polymerase II intronic transcription regulatory region sequence-specific DNA binding
Biological process: negative regulation of DNA-templated transcription; negative regulation of T cell differentiation in thymus; positive regulation of thymocyte apoptotic process; positive regulation of transcription by RNA polymerase III; response to antibiotic; snRNA transcription by RNA polymerase II; snRNA transcription by RNA polymerase III; T cell homeostasis; negative regulation of DNA-templated transcription, elongation; positive regulation of snRNA transcription by RNA polymerase II; negative regulation of transcription by RNA polymerase II
Cellular component: Cajal body; euchromatin; histone locus body; nuclear body; nucleoplasm; transcription elongation factor complex; chromatin; nucleus
Genetic constraint (gnomAD): Loss-of-function variants: 13 observed, 20.12 expected, observed/expected ratio (o/e) 0.65, 90% interval 0.42 to 1.03. The upper end of that interval is the gene's LOEUF score, 1.03, which puts it in group 4 of 6, group 1 being the genes least tolerant of losing a copy. Missense variants: 168 observed, 199.71 expected, observed/expected ratio (o/e) 0.84, 90% interval 0.74 to 0.96. Synonymous variants: 68 observed, 68.75 expected, observed/expected ratio (o/e) 0.99, 90% interval 0.81 to 1.21.
Homologues: Orthologues: chimpanzee ZC3H8 (99% identical), macaque ZC3H8 (97% identical), dog ZC3H8 (88% identical), pig ZC3H8 (82% identical), mouse Zc3h8 (80% identical), rabbit ZC3H8 (80% identical), rat Zc3h8 (77% identical), guinea pig ZC3H8 (72% identical), Caenorhabditis elegans T26A8.4 (18% identical). Paralogues in human: ZC3H6 (51% identical), ZC3H4 (34% identical).
Diseases named in the same sentence as ZC3H8 in open-access papers:
ZC3H8 is named in the same sentence as 6 diseases in open-access papers, as found by Europe PMC text mining. Sharing a sentence is not in itself a finding about the gene and the disease. The quoted sentences say what the papers report.
breast carcinoma (2 papers, 2018 to 2023). "ZC3H8 is overexpressed in a number of human and mouse breast cancer cell lines, and elevated mRNA levels are associated with a poorer prognosis for women with breast cancer." (PMID 30041613, 2018). "ZC3H8 expression has been reported to contribute to aggressive tumor cell behavior in breast cancer in vitro and in vivo models." (PMID 37958393, 2023). "We found that 7 of 9 tested mouse mammary carcinoma cell lines have 2 fold or greater elevated expression of Zc3h8 by examining mRNA levels using RT-qPCR." (PMID 30041613, 2018). "Mouse mammary tumor cells (cV1A 03–31) that have knocked down expression for Zc3h8 have a slower proliferation rate than cells transfected with the control pSilencer vector as determined by cell viability assay." (PMID 30041613, 2018). "We derived a number of cell lines from mouse mammary tumors and screened these for Zc3h8 expression compared to virgin mammary gland tissue or normal mouse mammary epithelial cells." (PMID 30041613, 2018). "Additionally, we show here that reducing expression of Zc3h8 in mammary tumor cell lines injected into mice greatly reduces the number and size of tumors that form." (PMID 30041613, 2018). "The noted amplification of ZC3H8 in human breast tumors, the potential regulatory effect of a known oncogene, CK2, and the developing understanding of post-transcriptional regulation contributing to breast cancer, provided the rationale for undertaking these experiments." (PMID 30041613, 2018).
diabetes (1 paper, 2020). "In addition, we identified nine genes (CABIN1, CKS1B, C19orf60, SDR39U1, SLC31A1, DNAJA4, ZC3H8, OTUD3 and UBALD1) not previously associated with diabetes, but that are known to be involved in processes potentially linked to β-cell dysfunction, such as cell turnover, oxidative stress and ER stress." (PMID 33575641, 2020).
tumor (2 papers, 2018 to 2023). "The studies presented here aimed to determine if ZC3H8 expression leads to invasive tumor cell behavior, and to determine if phenotypic changes are associated with the localization of ZC3H8 in nuclear subcompartments." (PMID 30041613, 2018). "Here we demonstrate that a novel component of nuclear bodies, ZC3H8, has a role in regulating cell behavior and promoting tumor formation." (PMID 30041613, 2018). "These experiments demonstrate that Zc3h8 expression contributes to aggressive tumor cell behavior in vitro and in vivo." (PMID 30041613, 2018). "We show that the level of Zc3h8 expression in murine mammary cells influences aggressive behavior in vitro and tumor formation in vivo." (PMID 30041613, 2018). "Taken with the overexpression of this gene in tumor cells, Zc3h8 appears to promote tumorigenesis." (PMID 30041613, 2018). "We wanted to know if our results from studying Zc3h8 in cells in culture could translate into changes in tumor growth in vivo." (PMID 30041613, 2018). "This could also account for the many changes in cell behavior that we have shown as a result of Zc3h8 knockdown or overexpression such as altered migration, invasion, proliferation, and growth in either soft-agar or spheroid plates in vitro and tumor formation in vivo." (PMID 30041613, 2018). "Tumor cell lines demonstrated varying ratios of Zc3h8 to Gata-3 levels, while stable overexpression did not decrease Gata-3 levels." (PMID 30041613, 2018). "Since Zc3h8 expression is elevated in many tumor cell lines, we stably transfected cells with vectors generating shRNA targeting Zc3h8 mRNA at one of two sites to generate tumor cell lines with reduced expression of Zc3h8 or negative control shRNA targets." (PMID 30041613, 2018).
cancer (1 paper, 2018). A tumor composed of atypical neoplastic, often pleomorphic cells that invade other tissues. "CK2 is an oncogene that regulates PML and ZC3H8-localized nuclear bodies, and is also a potential therapeutic target in the treatment of cancer." (PMID 30041613, 2018). "High expression of ZC3H8 decreases the probability of disease-specific survival, a trend seen in many datasets for breast and other cancers." (PMID 30041613, 2018). "Decreased expression of Zc3h8 in carcinoma cells decreased their growth and migration abilities and may have made these cells less aggressive." (PMID 30041613, 2018).
ZC3H8 also shares sentences with these, for which no sentence is quoted: colon cancer (1 paper); glioma (1).